CENPA (centromere protein A)
Description:
Histone H3-like nucleosomal protein that is specifically found in centromeric nucleosomes. Replaces conventional H3 in the nucleosome core of centromeric chromatin that serves as an assembly site for the inner kinetochore. The presence of CENPA subtly modifies the nucleosome structure and the way DNA is wrapped around the nucleosome and gives rise to protruding DNA ends that are less well-ordered and rigid compared to nucleosomes containing histone H3. May serve as an epigenetic mark that propagates centromere identity through replication and cell division. Required for recruitment and assembly of kinetochore proteins, and as a consequence required for progress through mitosis, chromosome segregation and cytokinesis.
Synonyms: CENP-A; CenH3
Tractability: Small molecule: a structure with a bound ligand is known. PROTAC: UniProt records ubiquitination sites on it; ubiquitination databases record sites on it.
Gene: Protein-coding gene on chromosome 2 (26,764,289 to 26,801,067, forward strand). Ensembl gene ENSG00000115163.
Subcellular location: Nucleus; Chromosome, centromere
Subcellular location (Human Protein Atlas): Nucleoplasm
Pathways (Reactome):
Cell Cycle: Amplification of signal from unattached kinetochores via a MAD2 inhibitory signal; Deposition of new CENPA-containing nucleosomes at the centromere; EML4 and NUDC in mitotic spindle formation; Mitotic Prometaphase; Resolution of Sister Chromatid Cohesion; Separation of Sister Chromatids
Signal Transduction: RHO GTPases Activate Formins
Gene Ontology:
Molecular function: protein binding; chromatin binding; nucleosomal DNA binding; structural constituent of chromatin; DNA binding; protein heterodimerization activity
Biological process: CENP-A containing chromatin assembly; establishment of mitotic spindle orientation; kinetochore assembly; mitotic cytokinesis; protein localization to chromosome, centromeric region; heterochromatin formation; mitotic metaphase chromosome alignment; protein localization to CENP-A containing chromatin
Cellular component: CENP-A containing nucleosome; chromosome, centromeric region; condensed chromosome, centromeric region; nucleoplasm; nucleosome; nucleus; cytosol; kinetochore; CENP-A containing chromatin; pericentric heterochromatin
Genetic constraint (gnomAD): Loss-of-function variants: 7 observed, 17.1 expected, observed/expected ratio (o/e) 0.41, 90% interval 0.23 to 0.77. The upper end of that interval is the gene's LOEUF score, 0.77, which puts it in group 3 of 6, group 1 being the genes least tolerant of losing a copy. Missense variants: 149 observed, 177.08 expected, observed/expected ratio (o/e) 0.84, 90% interval 0.74 to 0.96. Synonymous variants: 82 observed, 67.81 expected, observed/expected ratio (o/e) 1.21, 90% interval 1.01 to 1.45.
Homologues: Orthologues: chimpanzee CENPA (99% identical), macaque CENPA (93% identical), rabbit CENPA (82% identical), pig CENPA (77% identical), dog CENPA (76% identical), guinea pig CENPA (74% identical), mouse Cenpa (69% identical), zebrafish selenoh (54% identical), Caenorhabditis elegans hcp-3 (44% identical), Caenorhabditis elegans cpar-1 (41% identical), tropical clawed frog cenpa (36% identical). Paralogues in human: H3-3A (46% identical), H3-3B (46% identical), H3C1 (46% identical), H3C10 (46% identical), H3C11 (46% identical), H3C12 (46% identical), H3C13 (46% identical), H3C14 (46% identical), H3C15 (46% identical), H3C2 (46% identical), H3C3 (46% identical), H3C4 (46% identical), and 8 more.
Diseases named in the same sentence as CENPA in open-access papers:
CENPA is named in the same sentence as 100 diseases in open-access papers, as found by Europe PMC text mining. Sharing a sentence is not in itself a finding about the gene and the disease. The quoted sentences say what the papers report.
breast carcinoma (41 papers, 2010 to 2026). "The expression of CENPA has been reported to be associated with worse overall survival of some cancer types, such as ovarian cancer, liver cancer, breast cancer, and lung cancer." (PMID 39820192, 2025). "In breast cancer, elevated expression of CENPA is associated with cancer malignant progression and is a prognostic biomarker." (PMID 35496042, 2022). "Altered expression of CENPA was frequently observed in many types pf human malignancies including lung cancer, colorectal cancer, breast cancer, and HCC and implicated in cell cycle regulation, cell survival, and genetic stability." (PMID 32337237, 2020). "CENPA is also a potential prognostic biomarker of breast cancer, and the increased expression of this gene is associated with the poor survival of breast cancer patients." (PMID 28486948, 2017). "The study found that the expression level of CENPA was generally upregulated in various human cancer types, including but not limited to breast cancer, colorectal cancer, liver cancer, lung adenocarcinoma, ovarian cancer, and prostate cancer." (PMID 39620895, 2024). "A study on breast cancer indicated that the functional alteration of the CENPA-related coexpression network can affect and contribute to the development of various cancers by targeting the process of cell cycle progression." (PMID 37181805, 2023). "Genes extracted from the mRNA dataset, which show great significance in the development of breast cancer, are CENPA, MACF1, UGT2B7 and SEMA3B." (PMID 35205681, 2022). "The role of CENPA in some cancer types like prostate cancer, colon cancer, breast cancer, gastric cancer, and head and neck cancer was widely reported." (PMID 35359370, 2022). "Restoration assays also confirmed that MBNL1-AS1 suppressed the CENPA-mediated proliferation and stemness in breast cancer cells." (PMID 35518784, 2022). "We demonstrated that MBNL1-AS1 attenuated the abilities of breast cancer stemness and proliferation through reduced stability of CENPA mRNA, which unraveled a novel mechanism of MBNL1-AS1." (PMID 35518784, 2022). "CENPA was highly expressed in epithelial ovarian cancer, breast cancer, osteosarcoma, and lung adenocarcinoma." (PMID 32090070, 2020). "Increase in CENPA by immunohistochemical analysis in breast cancer samples trended towards an adverse outcome." (PMID 32090070, 2020). "TYMS physically interacts with two genes from the HER2 pattern -CENPO and CENPA and is a target gene of three Breast cancer drugs (Fluorouracil, Capecitabine and Gemcitabine)." (PMID 26892392, 2016). "CENPA is one of the genes included in some of the commercially available RNA based prognostic assays for breast cancer (BCa)—the 70 gene signature MammaPrint® and the five gene Molecular Grade Index (MGISM)." (PMID 24213134, 2011). "Further investigation of the interaction between HJURP and CENPA for breast cancer development will be carried out in our future studies." (PMID 20211017, 2010). "Surprisingly, HJURP levels were significantly and positively correlated with CENPA levels in human breast cancer cell lines and primary breast tumors." (PMID 20211017, 2010). "In this study we showed that HJURP mRNA levels are highly significantly correlated with CENPA mRNA levels in human breast cancer cell lines and primary breast tumors." (PMID 20211017, 2010). "In addition, studies also suggested the prognostic value of CENPA for a few cancer types, such as ovarian cancer, liver cancer, breast cancer, and lung cancer." (PMID 39820192, 2025).
breast carcinoma (continued). "We found that CENPA was upregulated in multiple tumours, including glioma, bladder cancer, breast cancer and liver cancer, among others which indicated that CENPA was widely expressed in various cancers and showed mRNA upregulation in both high‐grade and low‐grade glioma (p < 0.001)." (PMID 39620895, 2024). "Therefore, we elucidated a novel mechanism for how MBNL1-AS1 regulated the phenotype of BC and targeting the MBNL1-AS1/ZFP36/CENPA axis might function as therapeutic targets for breast cancer patients." (PMID 35518784, 2022). "Moreover, CENPA had predictive value in breast cancer and could contribute to disease progression as a marker of proliferation." (PMID 35518784, 2022). "While co-expression of CENPA and RRM2 have been previously analyzed in breast cancer, hepatocellular carcinoma, and in murine liver regeneration, their functional relationship has not been explored in PCa so far88–90." (PMID 41402347, 2025). "Altered expression of CENPA was found in multiple human malignancies including HCC, breast cancer, lung cancer, and colorectal cancer." (PMID 33391344, 2020). "Studies have shown that a two-gene ratio (HOXB13:IL17BR) and a five-gene (BUB1B, CENPA, NEK2, RACGAP1, RRM2) molecular grade index (MGI) are predictive of clinical outcomes among early-stage breast cancer patients." (PMID 23497539, 2013). "CENPA was an independent predictor for relapse in estrogen receptor- (ER-) positive breast cancer patients not receiving systematic therapy but not in ER-negative patients." (PMID 32337237, 2020). "Interestingly, the analysis of breast cancer datasets revealed that the expression of PICH correlates with that of mitosis-related genes, such as KIF4A, CEP55, MKI67, MELK, BUB1, CENPA, and AURKB." (PMID 31160555, 2019). "Centromere protein A (CENP-A) is over-expressed in colorectal cancer cell lines and suggested to be an independent prognostic marker for patients with estrogen receptor (ER)-positive breast cancer who received no systemic therapy." (PMID 33833984, 2021). "We next detected whether or not MBNL1-AS1 regulated the CENPA mRNA in breast cancer cells." (PMID 35518784, 2022). "For instance, in oestrogen receptor‐positive breast cancer patients who did not receive chemotherapy, CENPA could serve as an independent prognostic marker, and it was positively correlated with the Ki‐67 proliferation marker, which was also verified in the study of luminal A‐type breast cancer." (PMID 39620895, 2024).
colorectal cancer (24 papers, 2008 to 2025). A primary or metastatic malignant neoplasm that affects the colon or rectum. "Previous studies have found that CENPA is highly expressed in more than 20 cancer tissues, including BC, colorectal cancer (CRC), lung adenocarcinoma (LUAD) and ovarian cancer." (PMID 36163007, 2022). "Previous studies have revealed that CENPA is highly expressed in multiple cancer tissues, such as prostate cancer, hepatocellular carcinoma, invasive breast cancer, and colorectal cancer." (PMID 36341103, 2022). "Extensive studies have uncovered elevated CENPA levels in tumors and their effect in tumorigenesis, including colorectal cancer, breast cancer, gastric cancer, prostate adenocarcinoma, and lung cancer." (PMID 34627268, 2021). "Centromere protein-A overexpress in human primary colorectal cancer and HCC." (PMID 20021663, 2009). "Furthermore, the immunostaining with anti-CENPA antibodies revealed that the CENPA signals in tumour cells increase; therefore, the overexpression of CENPA may be critical in aneuploidy in colorectal cancers." (PMID 28486948, 2017).
hepatocellular carcinoma (22 papers, 2009 to 2026). A malignant tumor that arises from hepatocytes. "For instance, CENPA can act as a transcriptional regulator to promote hepatocellular carcinoma progression by cooperating with YY134." (PMID 40804263, 2025). "Previous studies report that CENPA is significantly overexpressed in hepatocellular carcinoma (HCC) tumor tissue." (PMID 34556750, 2021). "Previous publications revealed that CENPA was aberrantly overexpressed in hepatocellular carcinoma (HCC) tumor tissues." (PMID 32337237, 2020). "We identified six mRNAs (DPYSL4, HOMER1, ABCB6, CENPA, CDK1, STMN1) significantly associated with overall survival in the Cox proportional regression model for hepatocellular carcinoma." (PMID 31790363, 2019). "Exposure of human hepatoma cell lines to a low dose of the chemotherapy drug doxorubicin (generic) induces a senescence-like phenotype preceded by multinucleation and down regulation of multiple proteins with mitotic checkpoint functions, including CENPA." (PMID 20119530, 2009). "Lactylation of CENPA at K124 promotes its activation, increasing the expression of its target genes and accelerating tumor development in hepatocellular carcinoma (HCC)." (PMID 40584966, 2025). "This study is aimed at investigating the predictive value of CENPA in hepatocellular carcinoma (HCC) development." (PMID 32337237, 2020). "In hepatocellular carcinoma patients, CSN5 depletion took effective effects through downregulation of SMAD5-related pathways including CENPA, which represented a potential target for therapeutic approaches." (PMID 32090070, 2020). "Real-time PCR and tissue microarrays in patients suffering hepatocellular carcinoma (HCC) revealed that the expression level of mRNA encoding CENPA was higher than that in adjacent non-neoplasic liver tissue." (PMID 20119530, 2009). "CENPA could also activate downstream CCND1 and NRP2 by binding with the transcription factor YY1, thereby affecting the proliferation and invasion of hepatocellular carcinoma." (PMID 39620895, 2024).
lung carcinoma (16 papers, 2019 to 2025). "It has been reported that CENPA was highly expressed in lung cancer tissue and associated with poorer overall survival." (PMID 31324812, 2019). "Finally, we took the intersection of hub genes and risk genes and validated CENPA as both a tumor stemness regulator and a tumor prognostic factor in lung cancer." (PMID 35816352, 2022). "CENPA was described as relating to proliferation and prognosis in ovarian cancer, being crucial in prostate cancer growth, regulating metabolic reprogramming in colon cancer cells leading to its growth, and being associated with immune infiltration and prognosis in lung cancer." (PMID 36358698, 2022). "CDC20 together with CENPA, CDK1, AURKA, and TPX2 were also diagnostic biomarkers in LUAD, and elevated mRNA levels of CDC20 were correlated with poor prognosis of lung cancer." (PMID 34650921, 2021). "FOXM1 and MYBL2 motifs were enriched at CENPA, FOXM1, and MYBL2-linked enhancers we found in lung cancer cells (91.8% for a FOXM1 motif, 60.3% for an MYBL2 motif)." (PMID 32925947, 2020). "CENPA stands for centromere protein A, which was initiated as a novel biomarker not only for HCC but also for lung cancer." (PMID 34386813, 2021). "CENPA and CDK1 were also identified as prognostic markers of lung cancer." (PMID 35223866, 2021). "Lung squamous cell carcinoma (LUSC) showed the highest percentage of CENPA heterozygous amplification with no instances of heterozygous deletion, aligning with the earlier observation of a high frequency of gene amplification in lung cancer." (PMID 39820192, 2025). "However, why CENPA was upregulated in lung cancer has not been explored." (PMID 31324812, 2019).
systemic sclerosis (16 papers, 2013 to 2025). A chronic disorder, possibly autoimmune, marked by excessive production of collagen which results in hardening and thickening of body tissues. "CENPs, such as CENPA and CENPB, have been discovered to be immune autoantigens of systemic scleroderma." (PMID 36644760, 2022).
lung adenocarcinoma (15 papers, 2020 to 2025). A carcinoma that arises from the lung and is characterized by the presence of malignant glandular epithelial cells. "For example, overexpression of CENPA, which is identified as one of the key transcriptional regulators for lung adenocarcinoma, is associated with poor survival of lung adenocarcinoma patients." (PMID 36291764, 2022). "We identified individual lung adenocarcinoma enhancers linked to CENPA, FOXM1, or MYBL2 that were associated with poor patient survival." (PMID 32925947, 2020). "A recent study showed that CENPA could act as a novel diagnostic biomarker in lung adenocarcinoma." (PMID 33014809, 2020). "CENPA was closely associated with multiple immune cells across different cancers, particularly in lung squamous cell carcinoma (LUSC), lung adenocarcinoma (LUAD), glioblastoma multiforme (GBM), and thymoma (THYM)." (PMID 39820192, 2025). "We then applied QPCR to screen the expression of both in the lung normal epithelial cell line BSAE-2B and the lung adenocarcinoma cell line A549, and finally identified CENPA as the final study target." (PMID 35816352, 2022). "We found that overexpression of these 8 genes (CENPA, FAM83D, KNSTRN, CDKN3, CCNB1, CDK1, and CCNA2) is significantly associated with poor survival of lung adenocarcinoma patients (p-value < 0.05)." (PMID 36291764, 2022). "In this study, we also found that patients who are high in CENPA expression in lung adenocarcinoma hold a poor prognosis, which is consistent with previous findings." (PMID 35816352, 2022). "When we further examined the protein expression of CENPA using Western blot in A549 and NCI-H2126 lung adenocarcinoma cells, we found that the CENPA protein level was decreased upon siMYBL2 and siFOXM1 treatment." (PMID 36291764, 2022). "Among the activated transcriptional regulators, CENPA, MYBL2, and FOXM1 were linked to numerous cancer-specific enhancers and high expression of these regulators was observed in a subgroup of lung adenocarcinomas showing poor patient survival." (PMID 32925947, 2020). "CENPA was an independent prognostic factor for lung adenocarcinoma, primary osteosarcoma, and epithelial ovarian cancer." (PMID 32337237, 2020). "Prior to the present study on CENPA and NDC80, multiple studies have reported that these two factors were associated with poor prognosis of patients with lung adenocarcinoma, osteosarcoma, or other tumors." (PMID 32090084, 2020). "High expression of CENPA, FOXM1, and MYBL2 is particularly observed in a subgroup of lung adenocarcinomas and is associated with poor patient survival." (PMID 32925947, 2020). "Subsequently, CENPA was found to own the ability to regulate tumor stemness and proliferation in in vivo and in vitro studies However, our study appears to be the first to suggest that CENPA not only regulates tumor stemness but also has an independent prognostic effect in lung adenocarcinoma." (PMID 35816352, 2022). "Moreover, we identified novel downstream targets of MYBL2 and FOXM1 that include key oncogenes such as CENPA in lung adenocarcinoma." (PMID 36291764, 2022). "The results revealed that MYBL2, CENPA, FOXM1, E2F1, ZNF367, and HMGA1 are the most relevant upstream transcription factors in lung adenocarcinoma." (PMID 40885709, 2025). "For example, we showed that CENPA is one of the key targets of MYBL2 and FOXM1 in lung adenocarcinoma cells." (PMID 36291764, 2022). "CENPA combined with CDK1 and CDC20 can serve as a cluster of prognostic biomarkers for lung adenocarcinoma." (PMID 32922438, 2020). "In addition to CENPA, we identified additional potential target genes of MYBL2 and FOXM1 in lung adenocarcinoma." (PMID 36291764, 2022).